PERM1 (PPARGC1 and ESRR induced regulator, muscle 1)
Description:
Regulates the expression of selective PPARGC1A/B and ESRRA/B/G target genes with roles in glucose and lipid metabolism, energy transfer, contractile function, muscle mitochondrial biogenesis and oxidative capacity. Required for the efficient induction of MT-CO2, MT-CO3, COX4I1, TFB1M, TFB2M, POLRMT and SIRT3 by PPARGC1A. Positively regulates the PPARGC1A/ESRRG-induced expression of CKMT2, TNNI3 and SLC2A4 and negatively regulates the PPARGC1A/ESRRG-induced expression of PDK4.
Synonyms: C1orf170; MGC13275; RP11-54O7.8
Tractability: No criterion of Open Targets' tractability assessment is met for any kind of drug.
Gene: Protein-coding gene on chromosome 1 (975,194 to 982,134, reverse strand). Ensembl gene ENSG00000187642.
Subcellular location: Cytoplasm; Nucleus
Subcellular location (Human Protein Atlas): Nucleoplasm; Nuclear bodies
Pathways (Reactome):
Organelle biogenesis and maintenance: Transcriptional activation of mitochondrial biogenesis
Gene Ontology:
Biological process: response to muscle activity; regulation of DNA-templated transcription
Cellular component: cytoplasm; nucleus
Genetic constraint (gnomAD): Loss-of-function variants: 46 observed, 39.66 expected, observed/expected ratio (o/e) 1.16, 90% interval 0.92 to 1.48. The synonymous counts are far from expectation, so gnomAD's model fits this gene poorly and the ratio says little. Missense variants: 1,159 observed, 1,024.9 expected, observed/expected ratio (o/e) 1.13, 90% interval 1.08 to 1.19. Synonymous variants: 551 observed, 438.18 expected, observed/expected ratio (o/e) 1.26, 90% interval 1.17 to 1.35.
Homologues: Orthologues: chimpanzee PERM1 (95% identical), macaque PERM1 (79% identical), rabbit PERM1 (59% identical), dog PERM1 (54% identical), rat Perm1 (54% identical), mouse Perm1 (53% identical), zebrafish perm1b (18% identical). Paralogues in human: PRRT3 (13% identical).
Diseases named in the same sentence as PERM1 in open-access papers:
PERM1 is named in the same sentence as 19 diseases in open-access papers, as found by Europe PMC text mining. Sharing a sentence is not in itself a finding about the gene and the disease. The quoted sentences say what the papers report.
heart failure (5 papers, 2020 to 2025). Inability of the heart to pump blood at an adequate rate to meet tissue metabolic requirements. "Given that PERM1 is emerging as a potential therapeutic target for management of heart failure, it is important to determine unequivocally if, besides its effects on cardiac energy metabolism, PERM1 can also modulate cardiac mechanics." (PMID 40831501, 2025). "It is of interest that all of WT mice have EF above 50%, which corresponds to the normal range in humans, whereas about 7% of Perm1-KO mice have EF below 40%, which corresponds to the standard definition of heart failure with reduced EF (HFrEF)." (PMID 40831501, 2025). "More importantly, the initial response to phenylephrine-induced hypertrophy in cardiomyocytes, which mimics metabolic changes in pressure overload-induced heart failure, occurred in the reduced mRNA level of Perm1, followed by downregulation of ERRα an PGC-1α." (PMID 36419485, 2022). "The therapeutic potential of PERM1 in heart failure and cardiac metabolic syndromes should be tested in future studies." (PMID 36419485, 2022). "Together with the moderate downregulation of OXPHOS proteins and upregulation of glycolysis, our data suggest that metabolic profile in the Perm1 deficit heart mimics the metabolic remodeling at the early stage of heart failure." (PMID 36419485, 2022). "Genetic depletion of Perm1 partially mimics the downregulation of genes involved in fatty acid oxidation during heart failure." (PMID 36028747, 2022). "PERM1 deletion may contribute to the heart failure by altering mitochondrial morphology, decreasing OxPhos protein levels, and increasing glycolysis." (PMID 39457429, 2024). "However, the overall signaling vector from Smyd1 and Perm1 during evolving heart failure appears to be highly complex and needs further calrification." (PMID 32574189, 2020). "Similarly, the Perm1 protein level was significantly decreased in patients with advanced heart failure (55.2 ± 13.1% of donors, p<0.05)." (PMID 32574189, 2020). "It remains to be demonstrated whether the release of Smyd1 from the Perm1 promoter is a necessary or sufficient factor of Perm1 downregualtion in heart failure." (PMID 32574189, 2020). "It is possible that downregulation of Perm1 might occur during the early stage of heart failure under hemodynamic stress, leading to dysregulation of ERRα/PGC-1α signaling in mitochondrial bioenergetics." (PMID 32574189, 2020). "If so, maintaining Perm1 expression might attenuate the impairment of the ERRα/PGC-1α axis during pressure overload and prevent metabolic perturbations and the progression of heart failure at the early stage." (PMID 36419485, 2022).
amyotrophic lateral sclerosis (2 papers, 2024). Amyotrophic lateral sclerosis (ALS) is a neurodegenerative disease characterized by progressive muscular paralysis reflecting degeneration of motor neurons in the primary motor cortex, corticospinal tracts, brainstem and spinal cord. "The role of PERM1 has been reported in neurodegenerative diseases such as Parkinson’s disease, amyotrophic lateral sclerosis and Alzheimer’s disease." (PMID 38466466, 2024).
diabetes mellitus (2 papers, 2021 to 2023). A metabolic disorder characterized by abnormally high blood sugar levels due to diminished production of insulin or insulin resistance/desensitization. "These included proteins expressed by pancreatic islet cells (Ptch1, Disp1, Pck1, and Cacna1e) as well as proteins known to be associated with diabetes mellitus susceptibility or glucose metabolism (Adcy8, Perm1, Sorbs1, and Pla2g6)." (PMID 37934865, 2023). "In contrast to CK2, which is upregulated in skeletal muscle of patients with diabetes mellitus type 2, PERM1 is decreased, further supporting a close association with insulin-dependent metabolism and mitochondrial activity." (PMID 34385433, 2021).
acute intermittent porphyria (1 paper, 2024). Acute intermittent porphyria is the most frequent and the most severe form of the acute hepatic porphyrias. "PERM1 has been used as a marker of mitochondrial biogenesis in human peripheral white blood cells from acute intermittent porphyria patients, with lower serum PERM1 levels and mtDNA content being observed in patients compared to healthy controls." (PMID 39457429, 2024).
cerebrovascular diseases (1 paper, 2024). "The relationship between PERM1 and miRNA have rarely been reported in cerebrovascular diseases." (PMID 38466466, 2024).
desmoid-type fibromatosis (1 paper, 2024). "Studies on desmoid-type fibromatosis (DTF) tumors, including S45F and T41A, have identified PERM1 as a gene associated with differentially methylated regions between these tumor subtypes." (PMID 39457429, 2024).
Emery-Dreifuss muscular dystrophy (1 paper, 2023). Emery-Dreifuss muscular dystrophy (EDMD) is characterized by muscular weakness and atrophy, with early joint contractures and cardiomyopathy. "CSRP3, LMCD1, ALDOA, PERM1: candidate genes for Emery-Dreifuss muscular dystrophy that may also provide insight into frailty-related muscle weakness?" (PMID 37936983, 2023).
tumor (3 papers, 2017 to 2024). "In particular, genes such as MTND1P23, PLCH2, RNF223, PERM1, TAS1R3, and specific TMEM genes exhibit varied levels of expression across different tumour stages, thereby presenting a potential to discern early-stage ESCC from its later stages." (PMID 38562378, 2024).
cardiac diseases (1 paper, 2024). "PERM1 is downregulated in subjects suffering from cardiac diseases and experiencing pressure overload conditions." (PMID 39457429, 2024).
PERM1 also shares sentences with these, for which no sentence is quoted: Alzheimer disease (1 paper); Atrophy (1); bone osteosarcoma (1); diabetes mellitus type 2 (1); ischemic stroke (1); mammary tumors (1); metabolic disease (1); neurodegenerative disease (1); Obesity (1); Parkinson disease (1).